INS (insulin)
Diseases named in the same sentence as INS in open-access papers (continued):
Sharing a sentence is not in itself a finding about the gene and the disease.
atherosclerosis (continued). "Adiponectin also has the functions of anti-inflammation, anti-atherosclerosis and insulin sensitization." (PMID 33083291, 2020). "Though, we cannot exclude that a shared pathomechanism simultaneously induced atherosclerosis and reduced insulin clearance in the liver." (PMID 33384433, 2020). "With an insulin-sensitizing effect, adiponectin is positively associated with plasma HDL-C levels and protects against atherosclerosis." (PMID 33297350, 2020). "We demonstrated here that FBXW2 deficiency in macrophages counteracts the detrimental effects of HFD/WD on body weight, inflammation of adipose tissue, systemic insulin insensitivity and atherosclerosis." (PMID 33101872, 2020). "Hypothyroidism is associated with heart failure, diastolic hypertension, atherosclerosis, coronary artery disease (CAD), and decreased insulin sensitivity." (PMID 31857927, 2019). "APN plays an important role in regulating vasodilation, resisting inflammation and anti-arterial atherosclerosis, increasing insulin sensitivity, and regulating glycogen and lipid metabolism." (PMID 31969813, 2019). "It is well known that increased adiposity has adverse effects on insulin sensitivity, lipid metabolism, autonomic tone, fibrinolysis, and inflammation, which contributes to endothelial dysfunction and atherosclerosis." (PMID 31118920, 2019). "The inhibition of JNK is known to enhance insulin sensitivity and decrease atherosclerosis in animals." (PMID 31384309, 2019). "Soluble RAGE acts to sequester AGEs therefore, it is not surprising that administration of sRAGE both in vitro and in vivo attenuates AGE/RAGE-mediated complications such as atherosclerosis, and insulin resistance." (PMID 30781793, 2019). "These beneficial attributes of trans-PAO are reminiscent of its isomer's (cis-PAO's) role in preventing insulin resistance, hepatic lipogenesis, and atherosclerosis." (PMID 31422082, 2019). "It is reported that APN expressed in macrophages improves insulin sensitivity and protects against inflammation and atherosclerosis." (PMID 31969813, 2019). "Consumption of ferulic acid in animals has been shown to act to lower oxidative stress, increase insulin, decrease lipids and atherosclerosis and reduce blood pressure." (PMID 30646597, 2019). "Systemic inflammation is thought to contribute to decreased tissue sensitivity to insulin and the increased risk of cardiovascular disease in CKD by driving endothelial dysfunction and atherosclerosis." (PMID 30786864, 2019). "A close relative, cis-PAO, is produced by de novo lipogenesis and mediates inter-organ crosstalk, improving insulin-sensitivity and alleviating atherosclerosis in mice." (PMID 31422082, 2019). "The activation of this receptor activates several DNA transcription factors that are involved in several biological and metabolic pathways such as differentiation, atherosclerosis, adipogenesis, and insulin sensitivity." (PMID 31508564, 2019). "In mice, low dose chloroquine improves insulin sensitivity, decreases atherosclerosis, and suppresses activation of JNK in macrophages through pathways that require the presence of ATM." (PMID 31384309, 2019). "Ginkgo biloba extract (EGb) has definite pharmacological effects of protecting the vascular endothelium, improving insulin resistance, and preventing atherosclerosis." (PMID 31915506, 2019). "The beneficial metabolic effects of cis-PAO in high fat-fed mice include increased insulin sensitivity, suppressed hepatic gluconeogenesis, reduced vascular inflammation and atherosclerosis." (PMID 31422082, 2019). "The molecular interaction gene network map further depicts the interconnections between inflammatory, insulin, and lipid pathways reflected by metabolite markers of atherosclerosis." (PMID 31102408, 2019). "Free fatty acids (FFAs), high-sensitivity C-reactive protein (hs-CRP), adiponectin (APN), insulin (INS), and interleukin-6 (IL-6) can induce atherosclerosis through arterial inflammation." (PMID 31191115, 2019).
atherosclerosis (continued). "The adipokine adiponectin plays a key role in regulating insulin sensitivity and had previously been shown to play an anti-inflammatory role in atherosclerosis." (PMID 30369924, 2018). "Cytokines mediate many physiological and pathological metabolic processes, such as satiety and energy balance, inflammation, insulin resistance/sensitivity, angiogenesis, lipid metabolism, and atherosclerosis." (PMID 29631598, 2018). "The long-acting GLP-1 analogue liraglutide (LRG) exhibits pleiotropic effects on glucolipid metabolism, β-cell insulin secretion and anti-atherosclerosis." (PMID 29636047, 2018). "Although mitogen-activated protein kinase inhibition in endothelial cells and smooth muscle decreases the pro-atherogenic properties, this effect blocks the atherosclerosis pathway in mice by starting insulin." (PMID 29732028, 2018). "In contrast, peripheral adiposity, characterized by expansion of subcutaneous fat, is associated with improved insulin sensitivity and a lower risk of developing T2DM and atherosclerosis in comparison to central obesity." (PMID 29348470, 2018). "Altogether, smoking promotes atherosclerosis via several mechanisms including changes in blood clotting and lipids, endothelial function, insulin sensitivity, and autonomic tone." (PMID 30206258, 2018). "The miR-221/222 cluster is also considered a key player in vascular biology, as it contributes to vascular remodeling and plays a prominent role in atherosclerosis and in metabolic diseases, being involved in the regulation of insulin resistance." (PMID 28835705, 2017). "Adiponectin improves insulin sensitivity, glucose tolerance and lipid profile and decreases inflammation and atherosclerosis." (PMID 28185008, 2017). "MCP‐1 is an inflammatory hormone demonstrated to increase atherosclerosis and decrease insulin sensitivity." (PMID 28706732, 2017). "It has been reported to improve insulin sensitization, stimulate fatty acid oxidation, reduce inflammation, and inhibit atherosclerosis." (PMID 29201040, 2017). "MyD88 deficiency in endothelial cells results in a moderate reduction in diet-induced adipose macrophage infiltration, and M1 polarization, selective insulin sensitivity in adipose tissue, and amelioration of spontaneous atherosclerosis." (PMID 26959040, 2016). "PPARgamma is a nuclear receptor regulating inflammation, atherosclerosis, insulin sensitivity and adipogenesis." (PMID 27703845, 2016). "The results showed that ER-α expression was lower in the insulin-treated group than the control group, suggesting that insulin-induced atherosclerosis was mediated by decreased ER-α expression." (PMID 27832775, 2016). "Acting as a protein hormone, full length APN (fAPN) modulates numerous metabolic processes, sensitizes insulin sensitivity as well as protects against atherosclerosis." (PMID 27023866, 2016). "Among the consequences of PA-induced inflammation in endothelial cells is impaired insulin signaling and reduced nitric oxide production which is purported to precede the development of atherosclerosis." (PMID 27250532, 2016). "The mechanism through which insulin promotes atherosclerosis also involves epigenetic modifications; high insulin levels reduce methylation of the leptin and adiponectin promoters, which contributes to atherosclerosis." (PMID 27832775, 2016). "Obesity and type 2 diabetes patients are at increased risks of atherosclerosis and other cardiovascular complications since MPs are raised in blood plasma of diabetic, obese, and insulin-resistant individuals." (PMID 27066292, 2016). "The study began with our initial observation that the Elovl6-/- mice often suffered from growth retardation despite their significant metabolic advantages in insulin sensitivity and atherosclerosis." (PMID 27467521, 2016).
atherosclerosis (continued). "Adiponectin exerts insulin-sensitizing, anti-atherosclerosis and anti-inflammatory actions; indeed, adiponectin participates in many metabolic processes by modulating insulin sensitivity as well as glucose and lipid metabolism." (PMID 26875986, 2016). "High blood insulin concentration is an important factor in the incidence of atherosclerosis, especially for women in the latter stages of menopause." (PMID 27832775, 2016). "It is also possible that other sources of inflammatory proteins, such as the adipose tissue, contribute to insulin resistance with aging during atherosclerosis." (PMID 27135421, 2016). "This study revealed, for the first time, that insulin promotes atherosclerosis through epigenetic modifications, specifically, by inducing hypermethylation of the ER-α second exon region, which reduces ER-α expression and promotes atherosclerosis." (PMID 27832775, 2016). "Further study using euglycemic-hyperinsulinemic clamp test with tracer is necessary to clarify change of insulin sensitivity by a SGLT2i and its role in atherosclerosis." (PMID 26606676, 2015). "It is also likely that these disorders exhibit a deleterious effect on insulin sensitivity thereby enhancing atherosclerosis." (PMID 26265929, 2015). "It has a number of metabolic actions including increasing insulin sensitivity, diminishing atherosclerosis, and being generally anti-inflammatory." (PMID 26770217, 2015). "The Pune Children’s Study provides the first report of associations in India between glucose and insulin variables in childhood and a range of adult CVD risk factors including vascular markers of atherosclerosis." (PMID 25940643, 2015). "Adiponectin acts as an insulin-sensitizing adipocytokine and an anti-inflammatory factor especially with regard to atherosclerosis." (PMID 25628655, 2015). "The advantages of high cytokine response and a moderate insulin resistance in the past exceeded the potential harmful effect of atherosclerosis." (PMID 26693381, 2015). "AMP-dNM treatment restores insulin sensitivity in ob/ob mice and also inhibits atherosclerosis in APOE*3 Leiden as well as low-density lipoprotein receptor−/− mice." (PMID 26338710, 2015). "Liver X receptors (LXRs) have been recognized as a promising therapeutic target for atherosclerosis; however, their role in insulin sensitivity is controversial." (PMID 24972069, 2014). "Copeptin appeared to have an important role in metabolic response and subsequent development of atherosclerosis in insulin resistant, hyperandrogenemic PCOS patients." (PMID 24628831, 2014). "On the other hand, the present study is designed to clarify the efficacy and benefits of sitagliptin in preventing the progression of atherosclerosis in patients with insulin-treated T2DM free of apparent CVD in a multicenter PROBE trial." (PMID 24607023, 2014). "These moleculesare involved in many physiological processessuch as lipid metabolism atherosclerosis, bloodpressure regulation, insulin sensitivity, and angiogenesisand affect immunity and inflammation." (PMID 24520503, 2014). "A number of studies showed that insulin exerts protective effects against atherosclerosis through attenuating lipid metabolism, macrophage foam cell formation and oxidative stress." (PMID 24489861, 2014). "The aim of the present ongoing study is to assess the effects of sitagliptin on the progression of atherosclerosis in patients with insulin-treated T2DM using carotid intima-media thickness (IMT), an established marker of cardiovascular disease." (PMID 24607023, 2014). "Insulin promotes proliferation of VSMCs to induce formation of atherosclerosis through the MAPK pathway." (PMID 24604418, 2014). "Results will be available in the near future, and the findings are expected to provide new strategy to prevent atherosclerosis in patients with insulin-treated T2DM." (PMID 24607023, 2014). "The in vivo anti-atherosclerotic effects of insulin are far greater than the pro-atherosclerosis effects." (PMID 24669260, 2014).
atherosclerosis (continued). "The studies indicate that polymorphisms at the adiponectin locus are predictors of circulating adiponectin levels, insulin sensitivity, and atherosclerosis, highlighting the pivotal role of this adipokine in the modulation of metabolism and atherogenesis." (PMID 24575123, 2014). "Systemic deficiency of Arg-II reduces systemic and vascular inflammations in mice fed high cholesterol diet and high fat diet, and improves endothelial function in aging, reduces atherosclerosis, and improves insulin sensitivity and glucose homeostasis." (PMID 23781221, 2013). "Only rosiglitazone improved adipocyte function, restored insulin sensitivity, and inhibited atherosclerosis by decreasing lipid-loaded macrophages." (PMID 23620818, 2013). "Up to now, many researchers have investigated the correlations of disease duration, age at onset, metabolic control, and insulin doses with markers of early atherosclerosis (IMT, FMD) in ultrasound imaging." (PMID 24347835, 2013). "This indicates that increased CORT exposure per se has beneficial, long-lasting effects on atherosclerosis, but negatively affects body fat distribution and insulin sensitivity, by promoting fat accumulation in the long-term." (PMID 23717502, 2013). "Heart type free fatty acid binding protein appeared to have an important role in metabolic response and subsequent development of atherosclerosis in insulin resistant, hyperandrogenemic PCOS patients." (PMID 23249450, 2012). "These inhibitors were able to rescue well characterized animal models from postprandial hypertriglyceridemia and atherosclerosis with a concomitant improvement of insulin resistance and glucose tolerance." (PMID 22662181, 2012). "The IR Atherosclerosis Study (IRAS) and the Atherosclerosis Risk in Communities Study showed that insulin sensitivity (measured with an intravenous glucose tolerance test) correlates negatively with intimal-medial thickness of the carotid artery." (PMID 23293629, 2012). "The impact of inefficient insulin-mediated translocation on spontaneous atherosclerosis development was evaluated in 26 week old mice." (PMID 22701627, 2012). "Heart type FABP appeared to have an important role in metabolic response and subsequent development of atherosclerosis in insulin resistant, hyperandrogenemic PCOS patients." (PMID 23249450, 2012). "PPARγ is a ligand-activated nuclear transcription factor that plays important roles in cellular differentiation, cancer, inflammation, insulin sensitization, atherosclerosis, and metabolic diseases." (PMID 23199346, 2012). "This study was designed to investigate the insulin alteration as a consequence of hypercholesterolemic diet in rabbit model of early atherosclerosis." (PMID 23497719, 2012). "It has been recently demonstrated that down-regulation of MMP-9 via insulin treatment will result in reduction of intimal lesions in atherosclerosis-prone diabetic apoE (-/-) mice." (PMID 22114787, 2011). "It has been demonstrated that both FABP4 and FABP5 play important roles in the regulation of insulin sensitivity and the development of atherosclerosis and that their impacts differentially involve adipocytes or macrophages." (PMID 22121495, 2011). "Many studies suggest that PPARγ ligands not only ameliorate insulin sensitivity, but also have pleiotropic effects on the pathophysiology of atherosclerosis, cardiac hypertrophy, ischemic heart, and myocarditis." (PMID 20814542, 2010). "It regulates transcription of a number of genes involved in adipose differentiation and metabolism, insulin sensitivity, bodyweight regulation, atherosclerosis and inflammation." (PMID 20531941, 2010). "A 60-year-old insulin dependent, diabetic male with severe atherosclerosis requiring multiple amputations in the extremities in the past, with normal renal function presented with gangrene of glans penis." (PMID 19468442, 2009).
atherosclerosis (continued). "Peripheral vascular disease accelerated atherosclerosis (atheroscleropathy) ASO Insulin injection sites (sharp trauma)Necrobiosis lipoidica diabeticorum?" (PMID 15777477, 2005). "Other vasoprotective actions of insulin are its ability to increase NO production, act as an antioxidant and prevent atherosclerosis by reducing oxygen consumption." (PMID 16086844, 2005). "Collectively, these findings indicate that even in childhood, T1DM is associated with ultrasonographically detectable alterations in visceral fat distribution, insulin sensitivity, and lipid metabolism, accompanied by early indicators of subclinical atherosclerosis." (PMID 41597132, 2026). "The direct effects of insulin include stimulation of nitric oxide synthase (eNOS) in cells, increasing nitric oxide (NO) production, which promotes vasodilation and protects against atherosclerosis." (PMID 41007785, 2025). "IR is characterized by reduced sensitivity to the physiological effects of insulin, which can lead to abnormal glucose and lipid metabolism, directly drive atherosclerosis, and induce endothelial dysfunction, chronic inflammation, and oxidative stress, accelerating arteriosclerosis and thrombosis." (PMID 41299267, 2025). "Thus, FoxOs are activated in macrophages and VECs in an insulin-resistant animal model, but their pathophysiological role in atherosclerosis differs." (PMID 40141412, 2025). "In addition to oxidative stress and impaired insulin signaling, monocyte activation plays a critical role in the progression of endothelial dysfunction and atherosclerosis." (PMID 40429748, 2025). "This association could reflect the pro-atherogenic role of adipose tissue, which, through production of pro-inflammatory cytokines and insulin resistance, contributes to AS and the progression of atherosclerosis." (PMID 40573102, 2025). "This would clarify whether impaired insulin sensitivity contributes to the development of atherosclerosis or arises as a result of coronary disease-related inflammation and metabolic stress." (PMID 41375645, 2025). "Adiponectin enhances insulin sensitivity and prevents atherosclerosis." (PMID 40272732, 2025). "Additionally, they were enriched in biological pathways including insulin resistance, fluid shear stress and atherosclerosis, alcoholic liver disease, human papillomavirus infection, and longevity regulating pathways." (PMID 40313558, 2025). "These alterations not only worsen defects in insulin signaling but also promote endothelial dysfunction, chronic vascular inflammation, and myocardial energy imbalance, all of which play a critical role in the pathogenesis of atherosclerosis and heart failure." (PMID 40841630, 2025). "As an anti-inflammatory factor that enhances insulin sensitivity, adiponectin could also help modulate the oxidative modification of LDL in circulation, potentially reducing the risk of atherosclerosis." (PMID 40243674, 2025). "These abnormalities accelerate atherosclerosis and may impair insulin signaling via oxidative stress and inflammation." (PMID 39948676, 2025). "Additionally, in IR, insulin's action is shifted towards vasoconstriction, hypertrophy of smooth muscle cells and accelerated atherosclerosis via activation of the MAPK pathway." (PMID 40066350, 2025). "Furthermore, TNFRSF1A demonstrated substantial enrichment in the NF-kappa B signaling pathway, MAPK signaling pathway, Fluid shear stress and atherosclerosis, and Insulin resistance." (PMID 40918148, 2025). "Notably, pathways such as PI3K-Akt, MAPK, insulin, prolactin, ErB, apelin and lipid and atherosclerosis signaling are involved in glucose metabolism, protein synthesis, and energy metabolism." (PMID 41282288, 2025). "In general, insulin protects the cardiovascular system under physiological conditions; in insulin resistance, indirect processes favoring vascular dysfunction, inflammation, and atherosclerosis predominate." (PMID 41007785, 2025).